OR2M2 (olfactory receptor family 2 subfamily M member 2)
Description:
Odorant receptor.
Synonyms: OST423; OR2M2Q
Tractability: Antibody: its Gene Ontology location is reachable by antibodies, with high confidence; UniProt places it where antibodies can reach, with medium confidence; UniProt predicts a signal peptide or a membrane-spanning region.
Gene: Protein-coding gene on chromosome 1 (248,174,821 to 248,181,067, forward strand). Ensembl gene ENSG00000198601.
Subcellular location: Cell membrane
Pathways (Reactome):
Sensory Perception: Expression and translocation of olfactory receptors; Olfactory Signaling Pathway
Gene Ontology:
Molecular function: olfactory receptor activity; G protein-coupled receptor activity
Biological process: detection of chemical stimulus involved in sensory perception of smell; G protein-coupled receptor signaling pathway
Cellular component: plasma membrane; membrane
Genetic constraint (gnomAD): Missense variants: 465 observed, 434.83 expected, observed/expected ratio (o/e) 1.07, 90% interval 0.99 to 1.15. Synonymous variants: 167 observed, 154.92 expected, observed/expected ratio (o/e) 1.08, 90% interval 0.95 to 1.23.
Homologues: Orthologues: dog OR2M9 (70% identical). Paralogues in human: OR2M3 (82% identical), OR2M7 (82% identical), OR2M5 (81% identical), OR2M4 (66% identical), OR2T33 (51% identical), OR2T8 (51% identical), OR2T12 (50% identical), OR2V2 (49% identical), OR2L3 (49% identical), OR2T4 (49% identical), OR2T2 (48% identical), OR2T35 (48% identical), and 80 more.